ACE (angiotensin I converting enzyme)
Diseases named in the same sentence as ACE in open-access papers (continued):
Sharing a sentence is not in itself a finding about the gene and the disease.
hypertrophic cardiomyopathy (10 papers, 2010 to 2025). A condition in which the myocardium is hypertrophied without an obvious cause. "Search terms included “hypertrophic cardiomyopathy”, “angiotensin converting enzyme” (ACE) or “ACE” and “polymorphism or mutation”." (PMID 24204726, 2013). "ABPR: Abnormal blood pressure response; ACE: Angiotensin-converting enzyme; ARB: Angiotensin II receptor blocker; HCM: Hypertrophic cardiomyopathy; LV: Left ventricular; NYHA: New York Heart Association." (PMID 36601194, 2023). "For context, note that the average change in myocardial mass due to treatment of hypertrophic cardiomyopathy with ACE inhibitors over one year was reported as -45 g as measured by echocardiography." (PMID 25231607, 2014). "Some studies have reported that angiotensin converting enzyme (ACE) and angiotensinogen (AGT) genes have been associated with hypertrophic cardiomyopathy (HCM)." (PMID 24204726, 2013). "It has been found that numerous drugs used to treat hypertrophic cardiomyopathy, such as ACE inhibitors, beta-blockers and calcium channel blockers, may have antioxidant effects." (PMID 32000761, 2020). "H0UWL7/ACE and H0VDM6/ITGB1 have been recognized in hypertrophic cardiomyopathy disease pathways." (PMID 34466782, 2021).
obstructive sleep apnea (10 papers, 2014 to 2024). "We meta-analytically summarized the associations of angiotensin converting enzyme (ACE) gene insertion/deletion (I/D) polymorphism with ACE activity and obstructive sleep apnea syndrome (OSAS) to see whether ACE activity is causally associated with OSAS." (PMID 26486181, 2015). "Chronic refractory cough is a multifactorial symptom that can be the consequence of several pulmonary and extrapulmonary diseases including gastrooesophageal reflux, upper airway cough syndrome, obstructive sleep apnea, and medications such as ACE inhibitors." (PMID 36890510, 2023). "In fact, inhibitors of ACE have been shown to attenuate the arterial pressures and decrease the apnea and hypoapnea index in patients with obstructive sleep apnea." (PMID 25249981, 2014).
osteoarthritis (10 papers, 2007 to 2026). A noninflammatory degenerative joint disease occurring chiefly in older persons, characterized by degeneration of the articular cartilage, hypertrophy of bone at the margins and changes in the synovial membrane. "The connection between ACE polymorphisms and osteoarthritis susceptibility has been identified in genetic association studies in humans." (PMID 29134405, 2018).
pancreatitis (10 papers, 2010 to 2025). Inflammation of the pancreas. "The present findings suggest an increased risk of pancreatitis associated with ACE inhibitors and a reduced risk with ARBs, although the methodological limitations inherent in observational research preclude definitive conclusions." (PMID 41000144, 2025). "While gallstones and chronic alcohol use are primary causes, certain medications, including ACE inhibitors, statins, hormone-replacement therapies, diuretics, hypoglycemic agents, and steroids, can induce pancreatitis." (PMID 38910717, 2024). "The drugs implicated in causing pancreatitis include angiotensin-converting enzyme (ACE) inhibitors, statins, oral contraceptives/hormone replacement therapies (HRTs), diuretics, highly active antiretroviral therapy, valproic acid, and hypoglycemic agents." (PMID 39463520, 2024). "Here, we report a case in which a generally otherwise healthy patient presented with acute drug-induced pancreatitis caused by an angiotensin-converting enzyme (ACE) inhibitor taken eight weeks prior to the onset of symptoms." (PMID 34912629, 2021). "This counterintuitive result may reflect differences in background risk: in older individuals, pancreatitis may more often arise from other etiologies such as gallstones, alcohol use, or metabolic disorders, thereby attenuating the observable effect of ACE inhibitors." (PMID 41000144, 2025). "Given the rarity but clinical relevance of drug-induced pancreatitis, clinicians should remain vigilant when prescribing RAAS inhibitors, particularly ACE inhibitors." (PMID 41000144, 2025).
rhinitis (10 papers, 2009 to 2024). An inflammation of the mucous membrane lining the nose, usually associated with nasal discharge. "However, being aware of common yet less frequently recognized ACE inhibitor-induced upper respiratory symptoms such as nasal blockage, rhinitis, or postnasal drainage is essential." (PMID 39624172, 2024). "A comprehensive review of concomitant medications such as nonsteroidal anti-inflammatory drugs, angiotensin converting enzyme (ACE) inhibitors, beta-blockers, and intranasal decongestants helps diagnose or rule out other causes of rhinitis." (PMID 32508939, 2020).
SARS-CoV infection (10 papers, 2010 to 2023). "The disruption of the physiological balance between ACE/ACE2 and the angiotensin II/angiotensin system by SARS-CoV infection plays a pathogenic role in SARS-CoV–induced lung injury." (PMID 33390952, 2020). "Furthermore, ACE as a viral receptor is only expressed in the proximal renal tubules, which is parallel to the damaged site of the kidney in patients with SARS-CoV infection." (PMID 37645409, 2023). "Furthermore, the experimental models of SARS-CoV infection have demonstrated that abundant ACE expression can contribute to increased viral dissemination and disease severity." (PMID 38444707, 2023). "However, another study performed in Hong Kong did not discover a relationship between the ACE I/D polymorphism and the susceptibility to SARS-CoV infection or the outcome of SARS-CoV-infected patients." (PMID 33238910, 2020). "Previous studies have reported that the ACE2 levels decreased during the SARS-CoV infection, and ACE2 is known for its effect as the main counterregulatory enzyme to ACE that functions by the breakdown of degrading angiotensin II." (PMID 36052305, 2022).
xerostomia (10 papers, 2013 to 2025). Dryness of the mouth resulting from reduced salivary secretion. "Among the 7 hypertensive patients in our study, 3 had xerostomia, and they were using ACE inhibitors." (PMID 41353330, 2025). "Xerostomia has been specifically reported in relation to the use of ACE inhibitors and diuretics within antihypertensive therapy." (PMID 41353330, 2025). "In one of them the percentage and degree of xerostomia were collected in patients treated with ACE inhibitors, calcium channel blockers, β-adrenergic blockers, and diuretics obtaining a statistically significant higher percentage and level of xerostomia in the hypertensive group." (PMID 32260482, 2020). "In patients taking cardiological drugs (e.g., beta blockers, angiotensin-converting enzyme (ACE) inhibitors, and diuretics), we can observe reduced saliva production (hyposalivation (HS)), abnormal protein secretion into the saliva, and a subjective sensation of dry mouth (xerostomia)." (PMID 33477706, 2021). "In patients with HF, the use of multiple medications, such as diuretics, calcium channel blockers, ACE inhibitors, and SGLT2 inhibitors, can induce dry mouth (drug-induced xerostomia)." (PMID 40435119, 2025).
acute pancreatitis (9 papers, 2006 to 2025). An acute inflammatory process that leads to necrosis of the pancreatic parenchyma. "This meta-analysis aims to investigate the risk of acute pancreatitis associated with angiotensin-converting enzyme (ACE) inhibitors and angiotensin II receptor blockers (ARBs)." (PMID 41000144, 2025). "All studies assessed the risk of acute pancreatitis associated with ACE inhibitors or ARBs as drug classes, except one, which specifically evaluated losartan." (PMID 41000144, 2025). "PubMed and Embase were searched from their inception until April 10, 2025, to identify studies evaluating the risk of acute pancreatitis associated with ACE inhibitors and/or ARBs." (PMID 41000144, 2025). "Overall, ACE inhibitors increased the risk of acute pancreatitis (OR 1.33; 95% CI 1.12-1.58; I2 = 93%)." (PMID 41000144, 2025). "ACE inhibitors were associated with an increased risk of acute pancreatitis in case-control studies (OR 1.39; 95% CI 1.10-1.74; I2 = 88%), but not in cohort studies." (PMID 41000144, 2025). "Nonetheless, drug-induced acute pancreatitis is rare, and cases associated with ACE inhibitors are usually described in the literature as case reports, which hampers identification in clinical trials." (PMID 41000144, 2025). "An increased risk of acute pancreatitis associated with ACE inhibitors was also observed using the Knapp-Hartung method (OR 1.32; 95% CI 1.13-1.54; I2 = 93%)." (PMID 41000144, 2025). "Characteristics of observational studies evaluating the risk of acute pancreatitis associated with ACE inhibitors and ARBs." (PMID 41000144, 2025). "Current use of ACE inhibitors was associated with an increased OR of acute pancreatitis in the full multi-variable adjustment (OR = 1 · 11, 95% CI: 1 · 01–1 · 21)." (PMID 28270103, 2017). "Meta-analysis of the risk of acute pancreatitis associated with ACE inhibitors and ARBs." (PMID 41000144, 2025). "Our findings suggest a possible differential effect: ACE inhibitors may increase the risk of acute pancreatitis, while ARBs may have a protective effect." (PMID 41000144, 2025). "Some suggest that angiotensin-converting enzyme (ACE) inhibitors may be associated with at least a moderate increased risk of acute pancreatitis." (PMID 41000144, 2025). "Along these lines it was also suggested that bradykinin-mediated Ca2+ signaling in PSCs could contribute to causing an ACE blocker-induced acute pancreatitis." (PMID 27903970, 2017). "The aim of this systematic review and meta-analysis is to assess the risk of acute pancreatitis associated with RAAS inhibitors, specifically ACE inhibitors and ARBs." (PMID 41000144, 2025). "The incidence rate of acute pancreatitis among patients treated with ACE inhibitors was 0.98 cases per 1,000 person-years, while for ARBs it was 0.71 cases per 1,000 person-years." (PMID 41000144, 2025). "Pooled estimates of incidence rates of acute pancreatitis among patients treated with ACE inhibitors and ARBs in cohort studies were calculated using a random-effects model." (PMID 41000144, 2025). "The incidence rate of acute pancreatitis among patients treated with ACE inhibitors was estimated at 0.98 cases per 1000 person-years." (PMID 41000144, 2025). "In a rat L-arginine-induced acute pancreatitis model, pretreatment with an ACE inhibitor attenuated acute pancreatitis, reduced TNF-α, and infiltrated inflammatory cells in the pancreas." (PMID 34830195, 2021). "Recent studies suggest a crucial role for pancreatic renin-angiotensin system during chronic hypoxia in acute pancreatitis and for angiotensin converting enzyme (ACE) inhibitors in reducing pancreatic fibrosis in experimental models." (PMID 17163998, 2006). "The incidence rate of acute pancreatitis was higher with ACE inhibitors." (PMID 41000144, 2025). "ACE inhibitors increased the risk of acute pancreatitis (OR 1.33; 95% CI 1.12-1.58; I2 = 93%), whereas ARBs did not (OR 0.82; 95% CI 0.80-0.83; I2 = 0%)." (PMID 41000144, 2025).
acute pancreatitis (continued). "In addition, a recent study suggested an important role for the ACE/ACE2 imbalance in the pathogenesis of severe acute pancreatitis where the ratio of pancreatic ACE2 to ACE expression was significantly reduced and paralleled the severity of the disease." (PMID 30934934, 2019). "ACE and RAS activity is known to be enhanced during acute pancreatitis and chronic hypoxia in experimental animals." (PMID 17163998, 2006). "ACE-inhibitors have similar indications, but for which we did not hypothesize a protective relationship of acute pancreatitis." (PMID 28270103, 2017).
amyloidosis (9 papers, 2013 to 2025). A disorder characterized by the localized or diffuse accumulation of amyloid protein in various anatomic sites. "This review explores the emerging evidence behind the role of ACE in AD, the neuroprotective properties of monocytes overexpressing ACE and the therapeutic potential for exploiting this natural mechanism for amyloid clearance." (PMID 37427403, 2023). "In this study, the type of amyloidosis (AL vs. ATTR amyloidosis), renal function and tolerability of ACE-inhibitor therapy were associated with a better global and cardiac outcome in the contemporary cohort." (PMID 36419501, 2022). "In post-mortem analyses, cortical and perivascular ACE expression was upregulated in the brains of AD patients and correlated with parenchymal plaque load and extent of perivascular amyloid deposition, respectively." (PMID 28197669, 2017). "With respect to the issue of the concurrence of amyloidosis and increased ACE levels, scare evidence has been stated." (PMID 24826302, 2013). "As AD progresses through the brain, ACE activity may increase as a protective mechanism to promote amyloid clearance." (PMID 37427403, 2023). "It was thus hypothesized that increased ACE activity in CNS tissues is a protective response to increasing amyloid pathology." (PMID 28197669, 2017). "Furthermore, individuals with amyloidosis do not respond well to beta‐blockers or ACE inhibitors, medications commonly prescribed for patients with HCM." (PMID 39484862, 2025).
Fabry disease (9 papers, 2013 to 2026). Fabry disease (FD) is a progressive, inherited, multisystemic lysosomal storage disease characterized by specific neurological, cutaneous, renal, cardiovascular, cochleo-vestibular and cerebrovascular manifestations. "In Fabry disease, polymorphisms in ACE and eNOS have been linked to cardiovascular phenotype variability." (PMID 41567994, 2026). "Fabry disease symptomatic treatments include pain relief medications such as pregabalin, cardioprotective medications like ACE inhibitors, nephroprotective strategies involving ACE inhibitors or angiotensin receptor blockers, among others." (PMID 40075521, 2025). "In addition to specific treatments for Fabry disease, where there is evidence of Fabry nephropathy, proteinuria should be treated with antiproteinuric therapy, using angiotensin-converting enzyme (ACE) inhibitors or angiotensin receptor antagonists." (PMID 40673439, 2025). "Apart from general supportive treatments such as angiotensin converting enzyme (ACE) inhibitor and angiotensin receptor blockers, painkillers, antidepressants, acetylsalicylic acid, clopidogrel or similar, the current treatment of Fabry disease is enzyme replacement therapy (ERT)." (PMID 26557248, 2015).
Hepatic steatosis (9 papers, 2013 to 2025). Steatosis is a term used to denote lipid accumulation within hepatocytes. "Hepatic steatosis and NASH were induced in HepG2 cells by treatment with palmitic acid (PA, for 6 h) with/without pretreatment of ACE (25 or 50 μg/mL), AI (50 or 100 μg/mL), CL (50 or 100 μg/mL), curcumin (5 μg/mL), or scopoletin (5 μg/mL)." (PMID 29234397, 2017).
Hypercalciuria (9 papers, 2012 to 2025). "Laboratory findings revealed elevated C-reactive protein, hypercalciuria, and increased serum angiotensin-converting enzyme (ACE) levels." (PMID 41567898, 2025). "Normal serum ACE levels, absence of hypercalciuria, normal pulmonary function tests, slit-lamp eye examination, CD4 to CD8 ratio in bronchoalveolar lavage, and no detection of sarcoid granulomata in gastrocnemius muscle biopsy, made this diagnosis unlikely." (PMID 23078628, 2012).
kidney injury (9 papers, 2015 to 2024). Trauma to the kidney. "Moreover, it is well known that some of the most employed drugs in the battle against CKD progression (ACE inhibitors, AT1R blockers) can, controversially, cause acute kidney injury due to interstitial nephritis or hemodynamic mechanisms in some situations." (PMID 25607548, 2015). "Medications also differed between the groups, with patients in the kidney injury group more frequently receiving PPI, ACE inhibitors/angiotensin receptor blockers (ACEI/ARB), hypnotics, sedatives, and diuretics." (PMID 39668464, 2024). "First, we demonstrated that prenatal IA LPS induced CA-like responses in the fetal membranes, marked systemic immune responses at birth, and altered plasma levels of markers related to kidney injuries, including LRG1, ACE, and ICA." (PMID 33193334, 2020). "Lisinopril, a non-sulfhydryl ACE inhibitor, has been shown to exert scavenger action of free radicals and oxidants in male Wistar rats treated with doxorubicin to induce kidney injury." (PMID 35656292, 2022).
neuropathy (9 papers, 2012 to 2024). A disorder affecting the nervous system that manifests with pain, tingling, numbness, and/or muscle weakness. "The few exceptions related to hip circumference (p < 0.001), diastolic blood pressure (p < 0.001), haemoglobin A1c level (p < 0.001), creatinine clearance rate (p = 0.04), the use of ACE inhibitors (p = 0.01) and the presence of neuropathy (p = 0.008)." (PMID 22992779, 2012). "ACE inhibition and especially quinapril could be an alternative tool for the treatment of DN and the beneficial effect could be more prominent if the treatment begins at the early stages of neuropathy." (PMID 28373993, 2017).
Renal artery stenosis (9 papers, 2010 to 2024). The presence of stenosis of the renal artery. "One area of concern is the use of ACE inhibitors and ARBs in patients with bilateral renal artery stenosis." (PMID 23476746, 2013). "Dr. Rajesh Vijayvergiya, Assistant Professor of Cardiology: I just want to enquire whether this child was given any ACE inhibitors to control the BP as the deteriorating renal functions after ACE inhibitors can give a clue to bilateral renal artery stenosis." (PMID 20835329, 2010). "Angiotensin II-subtype-1 (AT1) receptor blockers or angiotensin-converting enzyme (ACE) inhibitors slow the progression of CKD, yet they are contraindicated in bilateral renal artery stenosis or in unilateral renal artery stenosis and (functional) single kidney situation." (PMID 24946879, 2014).
renovascular hypertension (9 papers, 2008 to 2025). High blood pressure secondary to renal artery stenosis. "The use of angiotensin converting enzyme (ACE) inhibitors, such as captopril, in conjunction with radionuclide renography has been shown to enhance sensitivity and specificity for detecting renovascular hypertension." (PMID 26459634, 2015). "Most physicians were correct in choosing calcium channel blockers and avoiding ACE inhibitors in renovascular hypertension in the case of a patient with a single functioning kidney." (PMID 18425285, 2008). "In addition, ACE was increased in the unclipped kidney while renin was elevated in the clipped kidney confirming previous findings of the RAS in animals with renovascular hypertension." (PMID 25706121, 2015). "Thus, many patients with renovascular disease will qualify for treatment with ACE inhibitors and/or ARA, because the survival of patients with renovascular hypertension has been shown to be better when an ACE inhibitor is part of the treatment." (PMID 18425285, 2008).
Sleep apnea (9 papers, 2011 to 2023). An intermittent cessation of airflow at the mouth and nose during sleep is known as sleep apnea. "Significant associations of symptoms of sleep apnea were observed with six rare variants [minor allele frequency (MAF) <1%] (located in ACE, AIFM3, LIPJ, MUC2, AP2A2, SH3BP1)." (PMID 29093733, 2017). "The upregulation of angiotensinogen, AT receptors and ACE expression could play a pathogenic role in the augmented activity of carotid chemosensitive cells and the inflammation of the carotid body in intermittent hypoxia, which is relevant to the early pathogenesis in sleep-disordered breathing." (PMID 25249981, 2014). "Case reports have shown that the use of ACE inhibitors promotes OSA-like symptoms, such as nasal obstruction, snoring, daytime sleepiness, and witness sleep apnea, and reduces CPAP adherence in patients with ACE inhibitor-related cough, but not in patients with good tolerance for ACE inhibitors." (PMID 35313858, 2022).